APOC4 (apolipoprotein C4)
Description:
May participate in lipoprotein metabolism.
Synonyms: Apo-CIV; ApoC-IV
Tractability: Antibody: its Gene Ontology location is reachable by antibodies, with high confidence; UniProt places it where antibodies can reach, with medium confidence; UniProt predicts a signal peptide or a membrane-spanning region.
Gene: Protein-coding gene on chromosome 19 (44,942,235 to 44,945,496, forward strand). Ensembl gene ENSG00000267467.
Subcellular location: Secreted
Pathways (Reactome):
Transport of small molecules: VLDL assembly; VLDL clearance
Signal Transduction: NR1H3 & NR1H2 regulate gene expression linked to cholesterol transport and efflux
Gene Ontology:
Molecular function: protein binding; lipid transporter activity
Biological process: lipid storage; triglyceride homeostasis; lipid metabolic process
Cellular component: high-density lipoprotein particle; very-low-density lipoprotein particle; extracellular region
Genetic constraint (gnomAD): Loss-of-function variants: 10 observed, 8.55 expected, observed/expected ratio (o/e) 1.17, 90% interval 0.71 to 1.82. That is too few expected variants to judge how well the gene tolerates losing a copy. Missense variants: 160 observed, 160.4 expected, observed/expected ratio (o/e) 1, 90% interval 0.88 to 1.14. Synonymous variants: 59 observed, 68.83 expected, observed/expected ratio (o/e) 0.86, 90% interval 0.69 to 1.07.
Homologues: Orthologues: macaque APOC4 (87% identical), chimpanzee APOC4 (63% identical), dog APOC4 (57% identical), pig APOC4 (57% identical), guinea pig APOC4 (57% identical), mouse Apoc4 (57% identical), rat Apoc4 (47% identical).
Diseases named in the same sentence as APOC4 in open-access papers:
APOC4 is named in the same sentence as 30 diseases in open-access papers, as found by Europe PMC text mining. Sharing a sentence is not in itself a finding about the gene and the disease. The quoted sentences say what the papers report.
coronary artery disease (4 papers, 2015 to 2024). "Similarly, SNP rs115045946 on chromosome 19 is near to gene APOC4, which is associated with coronary artery disease." (PMID 27980654, 2016). "For example, APOC4 has been detected at higher level in the High-Density Lipids isolated from plasma of patients with coronary artery disease compared to controls." (PMID 39405606, 2024).
Stroke (3 papers, 2022 to 2024). Sudden impairment of blood flow to a part of the brain due to occlusion or rupture of an artery to the brain. "With respect to proteome studies, APOC4 has been reported to be associated with coronary atherosclerosis, heart failure after AMI, and recovery from stroke." (PMID 38473885, 2024). "According to the literature, ApoC4 levels significantly correlate with NIHSS scores three months after stroke." (PMID 38732018, 2024). "APOC4 correlates with stroke recovery, while APOC2 is involved in the pathophysiology of post-stroke depression." (PMID 35754821, 2022).
atherosclerosis (2 papers, 2015 to 2025). A disease characterized by the build-up of fatty material and calcium deposition in the arterial wall resulting in partial or complete occlusion of the arterial lumen. "Hypertriglyceridemia and hypercholesterolemia are crucial risk factors for atherosclerosis, CAD and other arterial cardiovascular diseases, which indicated the important role of the two APOC4 polymorphisms during CAD development." (PMID 26129832, 2015). "An important role in the pathogenesis of atherosclerosis is played by the genes ALB, SHBG, APOC, APOC3, APOC4, and SAA4, of which APOC3 and APOC4 make a major contribution to the occurrence of atherosclerosis and also to insulin resistance and type 2 diabetes." (PMID 40361926, 2025).
breast carcinoma (2 papers, 2019 to 2025). "The patients exhibited significantly lower levels of key apolipoproteins, including apoA-1, apoA-2, apoC-2, and apoC-4, compared to luminal A, luminal B, and HER2-positive breast cancer patients (p-values ranging from 0.004 to 0.057)." (PMID 40430118, 2025).
hypertriglyceridemia (2 papers, 2015 to 2019). A laboratory test result indicating elevated triglyceride concentration in the blood. "Previous studies have demonstrated the effects of APOC4 and LPA in abnormal blood lipids including hypercholesterolemia or hypertriglyceridemia, indicating the potential role of APOC4 and LPA in the CAD development." (PMID 26129832, 2015).
Insulin resistance (2 papers, 2025 to 2026). Increased resistance towards insulin, that is, diminished effectiveness of insulin in reducing blood glucose levels. "APOA1, APOB, and APOC4 are core members of the apolipoprotein family that play crucial roles in regulating lipid metabolism and insulin resistance." (PMID 41056021, 2026).
amyloidosis (1 paper, 2016). A disorder characterized by the localized or diffuse accumulation of amyloid protein in various anatomic sites. "Based on the fact that affected patients with amyloidosis also displayed hypotriglyceridemia and increased plasma levels of HDL-C as compared with non-carriers in the family, we next screened several candidate genes including the APOC3, APOC1, APOC2, APOC4, APOA4, APOA5 and APOE genes." (PMID 26790392, 2016).
depression (1 paper, 2024). "A comparison of plasma protein expression between patients with depression and healthy controls has revealed that differentially expressed proteins, including apolipoproteins such as the APOE, APOC4, and APOA5, lead to significant alterations of lipid and metabolic functions." (PMID 39062058, 2024).
hepatitis B (1 paper, 2021). "Apoc-4 may affect the development of hepatitis B together with other members of the APOC family." (PMID 34746269, 2021).
hyperlipidemia (1 paper, 2023). "The present study demonstrated a significant upregulation in several apolipoproteins, including APOC1, APOB, APOC4 and APOL1, but also in LCAT, suggesting a dysregulation in lipoprotein metabolism that could be partially related to the hyperlipidemia in IMN patients." (PMID 37511514, 2023).
melanoma (1 paper, 2024). A malignant, usually aggressive tumor composed of atypical, neoplastic melanocytes. "•Proteins linked to melanoma development (PRG4, APOC4, SERPIND1, VWF, TNC and PLG) were identified in the plasma-derived EVs of patients with melanoma." (PMID 39405606, 2024). "Proteins (APOC4, PRG4, PLG, TNC, VWF and SERPIND1) and metabolites (lyso PC a C18:2, PC ae C44:3) previously associated with melanoma pathogenesis were identified as relevant in differentiating between disease stages." (PMID 39405606, 2024). "However, this study has identified other proteins in melanoma patient-derived EVs using machine learning algorithms, including PRG4 and APOC4, that have been linked to melanoma pathogenesis and progression." (PMID 39405606, 2024). "Similarly, APOC4 was identified as a 200-gene signature for melanoma diagnosis, in a study assessing the relevance of genes across multiple genetic microarray datasets." (PMID 39405606, 2024). "A grid search demonstrated that APOC4 and PRG4 could be used to distinguish melanoma patient EVs from healthy control with an accuracy of 73.4 %." (PMID 39405606, 2024). "Three proteins were commonly identified using the three algorithms as relevant in classifying EVs derived from patients with a melanoma diagnosis compared to those from healthy controls: specifically, Proteoglycan 4 (PRG4), Apolipoprotein C4 (APOC4) and Haptoglobin-Related Protein (HPR)." (PMID 39405606, 2024).
ovarian tumors (1 paper, 2018). "The significance of APOC2, APOC4, ORM1, SERPINA1, and SERPINA10 in differential diagnosis of ovarian tumors was not confirmed." (PMID 30065196, 2018).
scrapie (1 paper, 2011). A fatal disease of the nervous system in sheep and goats, characterized by pruritus, debility, and locomotor incoordination. "Although the expression of these genes was not modified in our study, the ApoC4 (apolipoprotein C-IV) gene was upregulated in our scrapie samples." (PMID 21629698, 2011).
infection (2 papers, 2021 to 2024). The state of being infected such as from the introduction of a foreign agent such as serum, vaccine, antigenic substance or organism. "In other word, APOC4 and CPB1 proteins were damaged, which may be associated with the degree of infection." (PMID 34035220, 2021).
tumor (2 papers, 2010 to 2023). "A study found that APOC1, APOC2, APOC3, and APOC4 were expressed differently in tumor and non-tumor tissues in hepatocellular carcinoma." (PMID 38067270, 2023).
APOC4 also shares sentences with these, for which no sentence is quoted: Alzheimer disease (2 papers); COVID-19 (2); heart failure (2); Hepatic steatosis (2); cognitive decline (1); colorectal tumours (1); coronary atherosclerosis (1); dyslipidemia (1); hepatoblastoma (1); Hypercholesterolemia (1); Hypertension (1); Obesity (1); ovarian carcinoma (1); Sepsis (1); type 2 diabetes (1).